POSTN (periostin)
Diseases named in the same sentence as POSTN in open-access papers (continued):
Sharing a sentence is not in itself a finding about the gene and the disease.
tumor (continued). "P4HA1 may promote tumor metastasis by enhancing the secretion of collagens, which form together with other extracellular molecules, such as fibronectin and periostin, fibrillar networks that regulate cell motility and invasion." (PMID 32053263, 2020). "Interestingly, we also found that miR-876 or POSTN was closely correlated to tumor thrombus, which arises from the vascular invasion and is an important biological feature of HCC." (PMID 33083453, 2020). "SLC35D3 was expressed in the epithelium derived tumor cells and POSTN in fibroblasts." (PMID 32049988, 2020). "Among them were known cancer/testis antigen genes (PNMA5, SPATA22, ROR1, and CT45A6) and some new candidates (PAX2, HES4, PEG10, NTN4, PDE10A, and POSTN), these genes could be useful tumor markers and potential therapeutic targets." (PMID 30922328, 2019). "Another study suggested that POSTN could regulate essential aspects of tumor biology, including proliferation, invasion, matrix remodeling, and dissemination to premetastatic niches in distant organs (Gonzalez‐Gonzalez & Alonso, 2018)." (PMID 31304688, 2019). "The pathological role of periostin in tumor progression remains controversial." (PMID 30621220, 2019). "ADAM8, besides cleaving important ECM components of the tumor stroma such as collagen I, fibronectin and periostin, can cluster with β1 integrin and could direct tumor cell invasion through localized proteolytic ECM degradation in protrusions of cancer cells." (PMID 31591367, 2019). "Additional RNAscope assays for IL6, CCL2, and POSTN were used to establish whether ANRIL correlated with increased tumor promoting cytokines." (PMID 31572679, 2019). "Together, these data suggest that secondary GBMs may have specific tumor progression pathways related to stress response and Periostin mediated immune infiltration." (PMID 31052505, 2019). "Strikingly, POSTN downregulation correlated inversely with tumor grade." (PMID 29946533, 2018). "Strong periostin staining of vessels was also seen within metastatic tumours." (PMID 30202513, 2018). "Because periostin expression was correlated with tumor size and invasiveness, we investigated whether periostin affects NSCLC proliferation and metastasis." (PMID 30131847, 2018). "Periostin constitutes an extracellular matrix protein that is expressed in several cancers; it is prominent in the stromal area during the patch and plaque stages of MF, but decreases during the tumor stage." (PMID 29915722, 2018). "TGF-β, which is known to activate tumor metastasis and invasion, might contribute to the poor prognosis in periostin-high patients." (PMID 30131847, 2018). "Periostin has been shown to induce proliferation in several tumor cell lines." (PMID 29946533, 2018). "Periostin is critical for the EMT process in several types of tumor cells." (PMID 29774119, 2018). "They showed that POSTN could be detected in the tumor stroma, cancer epithelial cells, as well as in peritumoral areas." (PMID 29946533, 2018). "Periostin plays a crucial role in inflammatory and tumor microenvironments." (PMID 29472541, 2018). "It is also important to note that there is no significant increase of any mouse periostin variants that are expressed in cancer-associated mouse stroma cells, further supporting the notion that periostin is specifically induced in human tumor cells." (PMID 29507310, 2018). "Therefore, periostin can directly stimulate the growth of CTCL tumor cells in addition to inducing a Th2-dominant environment in CTCL tumors." (PMID 29915722, 2018). "Tumor cells can secrete several chemokines, such as CC chemokine ligand 2, soluble colony-stimulating factor 1, stromal cell-derived factor, hepatocyte growth factor, and periostin (POSTN), to recruit TAMs in cancers." (PMID 30034397, 2018). "Since we observed only slight encapsulation of the primary tumors formed in the thigh of both periostin−/− and periostin+/+ mice, we speculate that periostin predominantly affected tumor proliferation in our study." (PMID 30131847, 2018).
tumor (continued). "Induction of human periostin knockdown delayed tumor growth in mice." (PMID 29507310, 2018). "Activated HSCs promote the tumor progression of heat-treated residual HCC through the release of POSTN, which could be inhibited by calcipotriol." (PMID 30400797, 2018). "Immunostaining of periostin in whole sections of HNSCC revealed variable expression in the stromal compartment of some tumours, which could explain the absence or low expression in our fibroblast matrisomes." (PMID 28102238, 2017). "Moreover, knockdown of periostin inhibited tumor formation and growth in subcutaneous xenografts, supporting a role for periostin in tumorigenesis in vivo." (PMID 29163770, 2017). "Periostin is involved in both normal physiological and pathological processes, including vascular disease, trauma repair, bone formation and formation of tumours." (PMID 28116073, 2017). "On contrary, relative expression of periostin is correlated with TNM although is not correlated with other parameters, suggesting that upregulation of periostin may be involved in tumor progression in NSCLC." (PMID 28088789, 2017). "Periostin functions as a potent chemo-attractant of monocyte-derived macrophages from the blood to the tumor microenvironment and maintain the M2 immune suppressive phenotype to promote tumor growth." (PMID 28740831, 2017). "Furthermore, these studies show that this involvement of periostin in tumor progression is a multimechanistic process." (PMID 28977942, 2017). "Periostin is overexpressed in various types of cancer tissues and may affect some aspects of biology, such as tumor angiogenesis, invasion and metastasis." (PMID 27816968, 2017). "A recent study supported that the secretion of granulin by metastasis-associated macrophages (MAMs) stimulates resident hepatic stellate cells (hStCs) into myofibroblasts that release periostin, thus leading to a fibrotic microenvironment in the liver that sustains metastatic tumor growth." (PMID 29197379, 2017). "Once stimulated by tumor cells, PSCs will perpetually be activated and produce excessive extracellular matrix to infiltrate and envelop the normal parenchyma via an autocrine periostin loop, creating a tumor-supportive microenvironment even under conditions of serum deprivation and hypoxia." (PMID 29163770, 2017). "It was shown that periostin levels correlated with tumor angiogenesis and tumor recurrence." (PMID 28754000, 2017). "In our study, higher concentrations of periostin effectively promoted tumor progression." (PMID 28977942, 2017). "Interestingly, IL-6, CCL2, and periostin were recently demonstrated to promote M2 macrophage polarization, and thus contribute to tumor growth." (PMID 28969635, 2017). "Given that WNT signaling is known to be recruited by the extracellular matrix protein PERIOSTINE (POSTN) in the stroma of at least certain tumor types and to participate in the steps required for cancer cell colonization and tumor progression, we next analyzed postn expression in our tumor models." (PMID 27776343, 2016). "The resistance to cisplatin induced by tumor environment POSTN may be dependent on tumor intrinsic PI3K/AKT pathway, which provides a window of opportunity for reversing platinum resistance by targeting AKT." (PMID 26716408, 2016). "The effect of POSTN in cancer stroma cells may activate AKT pathway in tumor and AKT inhibitor can be beneficial to augment the efficacy of existing cancer therapeutics." (PMID 26716408, 2016). "It would be valuable to conduct a clinical study investigating whether urinary EV periostin levels can be used to monitor tumor recurrence post TURBT." (PMID 26981774, 2016). "Besides, in our study, we observed VEGF expression was decreased in POSTN-silenced group by nude mice tumor immunochemistry." (PMID 27223086, 2016).
tumor (continued). "Finally, high levels of ERRα in tumor cells stimulated the pro-metastatic factor periostin expression in the stroma, suggesting that ERRα regulates the tumor stromal cell microenvironment to enhance tumor progression." (PMID 27776343, 2016). "Alternatively, or in addition, it may represent up-regulation of periostin expression in the tumor cells themselves." (PMID 26981774, 2016). "We believe that POSTN derived from HNC cells could only partially account for the tumor-promoting role of POSTN in tumor malignancy, which suggests that CAF-derived POSTN might be fundamental to many control processes in HNC microenvironment." (PMID 26857387, 2016). "Hence, we presumed that CAF-derived POSTN played its role in tumor progression partly by binding an integrin receptor." (PMID 26857387, 2016). "By adding POSTN protein, we showed increased POSTN protein expression in tumor cells in vitro." (PMID 26716408, 2016). "Several lines of evidence derived also from work with transgenic mice have shown suggested that the enhancement of Wnt activity, in the metastatic niche through the action of Periostin or by promoting the migratory behavior of circulating tumor cells, drives metastases in different cancer types." (PMID 26939070, 2016). "Existing evidence suggests that periostin can facilitate tumor metastasis through inducing EMT." (PMID 27034956, 2016). "NFs could trigger xenograft tumor growth of Rca-T cells and the POSTN-expressing NFs exhibited more significant stimulative effects on the xenograft tumor growth." (PMID 26857387, 2016). "In addition to being overexpressed by tumour cells, POSTN is also expressed in the stroma of normal stem cell niches and aids the metastatic success of circulating cancer cells." (PMID 26930720, 2016). "Most of the classifier genes (TMPRSS4, POSTN, SERPINB5) have been linked to migration, invasion, adhesion and metastasis of PDAC or other cancers, specifically associated with extracellular matrix and tumor microenvironment." (PMID 26993610, 2016). "Similarly, module 6 contains EMT inducer TWIST1, many extracellular matrix genes, as well as genes associated with senescence and autophagy, collagen genes, and the well validated predictor of tumor resectability, POSTN." (PMID 27287041, 2016). "Additionally, our data revealed that tumor stroma, especially CAFs, was the important source of POSTN in HNC tissues, and the fibroblast-secreted POSTN created a tumor-supportive microenvironment to facilitate the growth and metastasis of HNC cells." (PMID 26857387, 2016). "AKT inhibitor, MK-2206, can enhance the platinum response with patients with high POSTN expression in the tumor microenvironment, which may provide as a biomarker for clinical trial." (PMID 26716408, 2016). "POSTN also increases tumor angiogenesis and decreases tumor cell apoptosis in EOC." (PMID 26716408, 2016). "We observed that knockdown of POSTN in PSCs inhibited tumor growth compared with the control group." (PMID 27223086, 2016). "If up-regulation of POSTN by p73 leads to increased invasion, we would expect that the tumours in which this regulation is active and thus POSTN and p73 levels correlate, are more aggressive and have a worse prognosis than tumours where this axis is not functional." (PMID 26930720, 2016). "The mean tumor volume was much smaller in POSTN-silenced group than that in control group." (PMID 27223086, 2016). "In CRC with liver metastasis, POSTN is significantly higher in CD133+ than in CD133− tumor cells." (PMID 26556874, 2016). "POSTN promotes tumor progression and angiogenesis mediated by the VEGF receptor Flk-1/KDR." (PMID 27708222, 2016). "In conclusion, our findings elucidated the critical role of POSTN in PaC angiogenesis, POSTN could promote PaC metastasis and tumor angiogenesis via Erk/VEGFsignaling pathways, which may be serve as a marker in highly aggressive phenotype of PaC." (PMID 27223086, 2016).
tumor (continued). "Interestingly, the increased expression of POSTN was observed in the stromal cells around the tumor nodules in a time-dependent manner after Rca-T cells were implanted in the lung niche." (PMID 26857387, 2016). "Also, patients with high POSTN expression in cancer stroma had higher tumor recurrent rate than patients with low POSTN expression in cancer stroma after first treatment (52.7% and 25.6%, p < 0.001)." (PMID 26716408, 2016). "Besides, the tumor weight was decreased in POSTN-silenced group compared with the control group (2.58±0.21 g vs 1.31±0.19 g, P<0.05)." (PMID 27223086, 2016). "After evaluating the relationship between POSTN and tumor progression in vitro, we next analyzed whether the induced POSTN affected tumorigenicity in vivo using an Rca-T xenograft model in the BALB/C nude mice." (PMID 26857387, 2016). "Indeed, treatment of mice with POSTN specific DNA aptamers, single-stranded DNA oligonucleotides designed to bind and inhibit POSTN, was shown to decrease primary tumor growth and metastasis in a xenograft model of mammary tumorigenesis." (PMID 26086719, 2015). "Additionally, treatment of ovarian xenograft models with a neutralizing antibody to POSTN resulted in a reduction of metastatic potential and tumor growth, migration, and invasion." (PMID 26086719, 2015). "Because POSTN may be present at higher levels in immature cells than in differentiated counterparts, it can also aid in gauging the differentiation potential of tumor cells." (PMID 26023718, 2015). "Given that wound healing and tumor progression both involve cell proliferation and inflammation, we investigated whether POSTN, COL-I, and FN also influence tumor cell function." (PMID 26083413, 2015). "Interestingly, while strong peritumoral periostin staining was observed in all TMAs, the periostin staining in tumor epithelia was only detected in the TMAs from UCLA and UCI, but not in the TMAs from JHU." (PMID 25781169, 2015). "The sasRNA reported here may prove therapeutically relevant as a means for stably silencing Periostin activity and metastasis of tumour cells." (PMID 26543579, 2015). "POSTN may thus regulate tumor cell adhesion to COL-I and FN and thereby promote the extravasation of these cells to wound sites, a process that requires sequential cell attachment and detachment." (PMID 26083413, 2015). "In summary, we identified POSTN as a potential biomarker for the evaluation of tumor progression." (PMID 26023718, 2015). "However, most cancer studies have found periostin to be of tumour cell origin, with over-expression documented in a range of tumours, including lung, breast, ovary and pancreas." (PMID 25345775, 2015). "There is a significant correlation between high Periostin expression and poor prognosis in cancer patients, indicating its therapeutic potential as a gene-silencing target in an effort to reduce metastatic tumour formation." (PMID 26543579, 2015). "We observed reduced αSMA and periostin mRNA levels in DMOG‐treated tumours." (PMID 26323721, 2015). "This scaffold and remodeling function of POSTN may help us to understand its mechanism in regulating inflammation and tumor metastasis." (PMID 24563214, 2014). "Further understanding of the cellular and molecular mechanisms by which POSTN promotes metastasis and identification of POSTN functional modulators may hold promise for developing new strategies to inhibit tumor metastasis." (PMID 24009721, 2013). "A promising stroma specific protein which can be used to identify tumor-activated PSC is periostin." (PMID 23060813, 2012). "Although 100 ng/mL of periostin seems to be high concentration, we thought that concentration of periostin may be higher in local tumor area than in serum." (PMID 22952986, 2012). "Importantly, clinical studies of periostin expression in human cancers have demonstrated that increased expression of periostin correlates with the number of tumor blood vessels and with metastasis." (PMID 22952986, 2012).
tumor (continued). "Both stromal and epithelial POSTN expression were significantly increased in tumor tissues." (PMID 23273263, 2012). "In this study, we discovered a novel role for periostin in tumor lymphangiogenesis." (PMID 22952986, 2012). "Several of the upregulated genes encoded adhesion receptors, secreted proteins and cytoskeletal components, including CDH11, POSTN and MYO5B, along with RUNX1, a master regulator of differentiation processes in different tissues implicated in cell transformation and tumor progression." (PMID 21611158, 2011). "Activation of the Akt/PKB cellular survival pathway with consequential protection of tumor cells and endothelial cells from stress-induced cell death may contribute to the periostin-mediated drug resistance in cancer." (PMID 22110952, 2011). "Sliencing Periostin of LNCap cells also resulted in a significant decrease in the tumor burden." (PMID 21714934, 2011). "Additionally, the strong positive stromal Periostin expression in the tissues of all 18 xenografts revealed tumor-stroma interaction." (PMID 21714934, 2011). "The minimum tumor could been seen in the group of down-regulated Periostin LNCap cells and the maximum tumor could be found in the group of normal LNCap cells." (PMID 21714934, 2011). "Additionally, periostin overexpression is always correlated with increased tumor invasion and metastasis." (PMID 21504578, 2011). "Our study proposes periostin to be a novel stromal candidate marker of tumor prognosis that may also constitute potential therapeutic target in a broad range of carcinomas." (PMID 21611158, 2011). "As a result, the weak positive Periostin expressed tumor cells could be seen in the tissues of 6 xenografts from the group of down-regulated Periostin LNCap cells which had a significant decrease of the amount of Periostin compared to the other two group." (PMID 21714934, 2011). "Periostin may play a role in focal adhesion, and promote Akt activation, leading to tumor and endothelial cell survival." (PMID 21489260, 2011). "While the tumor-suppressive properties documented for periostin in these studies remain to be reconciled with a large body of literature describing periostin as tumor promoting, these results demonstrate the functional significance of the periostin C-terminal region as a whole." (PMID 20109226, 2010). "We observed overexpression of periostin in both tumor and stromal cells." (PMID 24281036, 2010). "In 72% of ESCC cases, expression of periostin was detected both in tumor and stromal cells." (PMID 24281036, 2010). "Overall, for most tumor types tested in this study, our data revealed highly variable POSTN expression levels in both tumors and normal tissues, suggesting that larger numbers of samples should be tested to address periostin expression in tumors more significantly." (PMID 18086302, 2007). "Most of primary tumours, which showed metastasis were positive for Periostin." (PMID 17060937, 2006). "Cumulative findings suggest that high expression of Periostin may be a common event of tumour development in cancer." (PMID 17060937, 2006). "In addition, the regulation of tumor-associated macrophages (LTBP-1 and POSTN) could make the tumor microenvironment more favorable for the spread of cancer cells." (PMID 40143207, 2025). "In addition, our study demonstrated a statistically significant relationship between high levels of POSTN expression in tumor cells and tumor stroma and shorter survival in patients with NSCLC overall and in individual histological subtypes of NSCLC, namely AC and SCC." (PMID 39272978, 2024). "In turn, myMAF-secreted periostin directly promotes cancer cell proliferation, whereas myMAF and cancer-cell secreted Osteopontin fosters an immunosuppressive macrophage phenotype, thereby curbing an efficient anti-tumour immune response and permitting metastatic outgrowth." (PMID 38678021, 2024).